IGFBP3 (insulin like growth factor binding protein 3)
Diseases named in the same sentence as IGFBP3 in open-access papers (continued):
Sharing a sentence is not in itself a finding about the gene and the disease.
breast carcinoma (continued). "In meta-analyses of the association between the blood concentration of IGFBP-3 and breast cancer risk, high blood levels of IGFBP-3 were associated with an increased risk of premenopausal breast cancer but not with that of postmenopausal breast cancer." (PMID 17210081, 2007). "Most studies on the association between IGFBP-3 and breast cancer risk have been focused on the level of circulating IGFBP-3." (PMID 17210081, 2007). "The polymorphism P0453 of IGFBP3 also showed a slight increase in the mean circulating IGF-I protein levels and one IGFBP3 haplotype showed an increase in risk of breast cancer, under a recessive model." (PMID 16404426, 2006). "The association between the molar ratio of IGF-I/IGFBP-3 and breast cancer risk was similar to that of IGF-I adjusted for IGFBP-3 (OR 1.61; 95% CI: 0.75–3.47 in the highest vs the lowest third of IGF-I/IGFBP-3 concentration; test for linear trend; P=0.19)." (PMID 15756268, 2005). "Although high levels of IGFBP-3 in breast cancers are associated with poor prognostic features of the tumour, few studies have substantiated any significant implications on patient outcome[B24,25]." (PMID 15642160, 2005). "The aim of this study is to examine the associations between serum concentrations of IGF-I, IGF-II and IGFBP-3 and subsequent breast cancer risk in a case–control study nested within a cohort of women on the island of Guernsey." (PMID 15756268, 2005). "Previously, high IGFBP-3 levels in breast cancers have been determined by enzyme-linked immunosorbent assay and immunoradiometric assay methods." (PMID 15642160, 2005). "Invasive breast cancers expressing IGFBP-3 showed an association with poor prognostic features including increased proliferation, ER negativity and HER-2 overexpression, with possible implications for patient outcome." (PMID 15642160, 2005). "We have demonstrated a tumour-associated upregulation of cytoplasmic IGFBP-3 epithelial expression in invasive and non-invasive breast cancers, with similar patterns of immunoreactivity." (PMID 15642160, 2005). "Yet, for pre-menopausal breast cancer, there is a positive association between circulating IGFBP-3 and cancer risk." (PMID 15354219, 2004). "Furthermore, insulin-like growth factor binding protein-3 (IGFBP-3) has been implicated in promoting breast cancer growth in immune-tolerant mouse models by inhibiting T cell infiltration into the TME." (PMID 41200178, 2025). "The observed association between the IGFBP-3 A-202C polymorphism and breast cancer risk may be explained through its role in regulating IGF-1 bioavailability and apoptosis." (PMID 40493660, 2025). "These collective findings suggest that the IGFBP-3 A-202C polymorphism could serve as a valuable genetic marker for breast cancer susceptibility and progression." (PMID 40493660, 2025). "Genotype distribution and breast cancer risk for IGFBP-3 A-202C polymorphism." (PMID 40493660, 2025). "For instance, a large case-control study in the UK, including 4,647 breast cancer cases and 4,564 controls, found that the AA genotype of IGFBP-3 rs2854744 was associated with increased circulating IGFBP-3 levels and a modestly reduced risk of breast cancer (OR = 0.87; 95% CI 0.77, 0.99, p = 0.03)." (PMID 40493660, 2025). "The demonstration of the involvement of IGFBP-3 in the senescence of breast cancer cells in this study presents further evidence of a potential mechanism for the loss of cell viability effect of IGFBP-3, and a potential therapeutic strategy for cancer treatment." (PMID 37253773, 2023). "Circulating concentrations of IGF-1 AND IGFBP-3 are associated with breast cancer risk." (PMID 36672557, 2022). "When stratified by levels of insulin and the IGF axis biomarkers, participants with low insulin (HR: 1.42; 95% CI: 1.11–1.82), low C-peptide (HR: 1.41; 95% CI: 1.10–1.80), and low IGF1/IGFBP3 ratio (HR: 2.55; 95% CI: 1.18–5.49) exhibited increased risk of breast cancer recurrence." (PMID 34456877, 2021).
breast carcinoma (continued). "High age-adjusted IGF-I (T3: OR 2.00, 95% CI 0.92–4.37; Ptrend=0.086) as well as high age-adjusted IGFBP-3 levels (T3: OR 2.10, 95% CI 1.06–4.15; Ptrend=0.031) were associated with higher odds of breast cancer recurrence compared with low IGF-I or IGFBP-3 levels." (PMID 33767994, 2021). "With few exceptions, there exists limited data regarding whether IGF-1/IGFBP-3 biomarkers may be associated with cancer in women at high risk of breast cancer." (PMID 33092613, 2020). "In tumours from patients with breast cancer, high levels of IGFBP-3 have been consistently associated with worse outcome and may therefore be a promising potential therapeutic target." (PMID 33352865, 2020). "The result suggests that "soy protein intake may negatively modulate the effect of IGF-I and may positively modulate the effect of IGFBP-3 levels on premenopausal breast cancer risk"." (PMID 32528752, 2020). "As the main binding protein of IGF-1, insulin-like growth factor binding protein-3 (IGFBP3) has been reported to be linked to pathogenesis of cancers by exerting tumor suppressor activity in breast cancer and pro-tumor effects in oral squamous cell carcinoma and lung cancer." (PMID 32312329, 2020). "Using conditional logistic regression, we estimated the association between IGF-1 and IGFBP-3 levels and breast cancer risk and examined whether this risk differed by predicted absolute breast cancer risk based on pedigree models." (PMID 33092613, 2020). "However, evidence connecting the elevated levels of IGFBP-3 to the risk of later onset of breast cancer development is conflicting." (PMID 31752829, 2019). "This might seem contradictory to a large volume of epidemiology linking circulating total IGF‐I with increased risk of pre‐ and postmenopausal breast cancer, and circulating IGFBP‐3 and postmenopausal breast cancer." (PMID 29722920, 2018). "Interestingly, low levels of DNMT3a correlates well with a high IGFBP3 expression and associate with a poor distant metastasis-free survival of breast cancer patients." (PMID 28393842, 2017). "Studies have also implicated IGFBP3 in breast cancer risk, although it is unclear whether this is a result of IGF-dependent or -independent functions." (PMID 27376028, 2016). "Both Epidemiological and molecular studies have shown that vitamin D, directly or indirectly, may inhibit IGF-I and enhance IGFBP-3 effects in breast tissue, that may reduce breast density and breast cancer risk." (PMID 27564705, 2016). "Similarly, cases expressing IGFBP3 were at higher risk of all-cause and breast cancer mortality (HRmort = 5.16, 95% CI: 1.27–20.94 and HRmort = 8.60, 95% CI: 1.84–40.15), respectively)." (PMID 25619494, 2015). "Much of the association was limited to premenopausal women, particularly among those with high circulating IGF-1 and low IGFBP-3 levels, suggesting that vitamin D may modulate MD and breast cancer risk via IGF signaling." (PMID 28480224, 2015). "We examined the expression profiles of the IGF1, IGF1R, IGFBP2 (IGF-binding proteins), and IGFBP3 proteins in breast tumor tissue and their relationships with all-cause and breast cancer-specific survival up to 17 years postdiagnosis in a multiethnic series of 358 patients in Hawaii, USA." (PMID 25619494, 2015). "However, perhaps the earliest and best-documented association of IGFBP-3 with poor patient outcome is in breast cancer." (PMID 26221601, 2015). "The relationship of IGF1 (and IGFBP3) with breast-cancer risk factors is also unclear." (PMID 20472501, 2010). "The levels of IGF1 and IGFBP3 combined may be associated with breast cancer by stimulating proliferation of breast epithelial cells." (PMID 20302654, 2010).
breast carcinoma (continued). "Most prospective studies of IGF1 and breast-cancer risk have also reported on IGFBP3, to explore the hypothesis that women with a high concentration of IGF1 relative to IGFBP3 are at an increased risk of breast cancer." (PMID 20472501, 2010). "Further, increased IGFBP3 expression has also been linked to renal cell carcinoma, breast cancer, and metastatic melanoma, suggesting that IGFBP3 may contribute to tumorigenesis or disease progression." (PMID 19903356, 2009). "Association of tagging SNPs of IGFBP1 and IGFBP3 and breast cancer risk in the BPC3." (PMID 18596909, 2008). "Our data show that lower WHR, lower alcohol intake, and higher energy intake or nulliparity are associated with higher levels of intact IGFBP-3 whereas associations in the opposite direction are observed between these breast cancer risk factors and fragmented or total IGFBP-3 levels." (PMID 18471292, 2008). "Finally, the cross-sectional design of the study does not allow us to determine the temporality of the relation between IGFBP-3 levels and breast cancer risk factors." (PMID 18471292, 2008). "However, associations of IGFBP-3 levels with breast cancer risk have been inconsistent, possibly due to the different predominant forms of circulating IGFBP-3 (intact versus fragmented) that were measured in these studies." (PMID 18471292, 2008). "However, a recent nested case-control study in the European Prospective Investigation into Cancer and Nutrition (EPIC) showed an increased risk for breast cancer with high circulating IGFBP-3 after 50 years of age." (PMID 17210081, 2007). "Moreover, none of the studies have directly evaluated the association between IGFBP3 mRNA expression and breast cancer survival." (PMID 17210081, 2007). "This variation may be important because epidemiological evidence suggests that elevated levels of serum IGF-I, as absolute concentrations or relative to IGFBP-3, may be associated with an increased risk of breast cancer in premenopausal women." (PMID 15756268, 2005). "In summary, the results of this prospective study are consistent with the hypothesis that premenopausal women with a relatively high circulating concentration of IGF-I and low IGFBP-3 are at an increased risk of developing breast cancer." (PMID 15756268, 2005). "Our finding of IGF-II and IGFBP-3 in association with unfavourable prognostic indicators of breast cancer suggests that IGFs may be involved in the progression of breast cancer." (PMID 8883411, 1996). "In addition, five SNPs in three genes (ADIPOQ rs182052, rs822391 and rs7649121, CARTPT rs3846659, and LEPR rs12059300) had an effect modification on the association between IGFBP-3 serum concentration and breast cancer risk (Pinteraction < 0.05, adjusted Pinteraction < 0.20)." (PMID 35115550, 2022). "However, the association of high IGFBP-3 expression with poor outcome in aggressive breast cancer may, in addition to reflecting enhanced tumor growth reflect altered responsiveness to anticancer therapies." (PMID 26221601, 2015). "Thus in some breast cancers high IGFBP-3 expression might be associated with treatment resistance rather than sensitivity." (PMID 26221601, 2015). "However, IGFBP3 overexpression in breast cancer is linked to poor prognosis." (PMID 24920244, 2014). "In addition, factors regulating the ossification process, such as insulin, insulin-like growth factor type 1, insulin-like growth factor type 2, and insulin-like growth factor binding protein 3, may also have association with the breast cancer risk." (PMID 24069386, 2013). "We recently reported that increased birthweight and decreased body size in youth and adolescence were associated with higher IGF-1 and IGFBP-3 levels in adulthood, suggesting that early life body size may act on breast cancer risk through its influence on hormone levels in adulthood." (PMID 22894543, 2012).
breast carcinoma (continued). "Some published results have shown an association between circulating IGF1 and breast-cancer risk, but it has been unclear whether this relationship is consistent or whether it is modified by IGF binding protein 3 (IGFBP3), menopausal status, oestrogen receptor status or other factors." (PMID 20472501, 2010). "In contrast, recent data from the New York University Women's Health Study suggested that, among young women, high levels of functional IGFBP-3 could be associated with a reduction of breast cancer risk whereas high levels of total IGFBP-3 could be associated with an increased risk of breast cancer." (PMID 18471292, 2008). "Thus, the variation in intact/functional versus total IGFBP-3 levels among subjects may differently modulate the risk of breast cancer." (PMID 18471292, 2008). "The aim of this study was to examine whether circulating levels of intact IGFBP-3 and total IGFBP-3 were differently associated with several breast cancer risk factors, including mammographic breast density, a strong and independent breast cancer risk indicator." (PMID 18471292, 2008). "In breast cancer, IGFBP3 promotes the phosphorylation and nuclear translocation of EGFR and DNA-PKcs by facilitating their binding." (PMID 41199784, 2025). "The IGFBP-3 A-202C polymorphism, especially the CC genotype, is strongly associated with elevated serum IGFBP-3 and IGF-1 levels and increased breast cancer risk, highlighting its potential as a biomarker for breast cancer screening and risk stratification." (PMID 40493660, 2025). "By examining the IGFBP-3 A-202C polymorphism in the context of both IGFBP-3 and IGF-1 serum levels, we clarify the role of this polymorphism as a biomarker for early breast cancer detection, particularly in Palestinian women." (PMID 40493660, 2025). "For instance, exogenous IGFBP3 has been shown to significantly inhibit the growth of human breast cancer cells through unique interactions with cell surface proteins." (PMID 40443651, 2025). "Genetic polymorphisms within the IGFBP-3 gene can modulate circulating IGFBP-3 levels and impact a person’s vulnerability to different carcinomas, including breast cancer." (PMID 40493660, 2025). "The study examined the distribution of IGFBP-3 A-202C genotypes among 112 breast cancer cases and 222 healthy controls, stratified by menopausal status." (PMID 40493660, 2025). "Taken together, these data suggest that IGFBP-3 is a key component in developing Ful resistance in breast cancer cells (Graphical Abstract)." (PMID 39619437, 2024). "Fulvestrant has been shown to modulate IGFBP-1 levels in vitro and IGFBP-3 levels in the serum of breast cancer patients." (PMID 39619437, 2024). "Previous studies have shown that the antiproliferative effect of IGFBP-3 in human breast cancer cells occurs via binding to cell surface proteins." (PMID 39272080, 2024). "Stable expression of IGFBP-3 in MCF-7 breast cancer elicited resistance to the selective estrogen receptor degrader (SERD) fulvestrant (Ful), and MCF-7 cells with acquired resistance to Ful (MCF-7FulR) have higher IGFBP-3 expression than parental cells." (PMID 39619437, 2024). "In ERα positive breast cancer cells, IGFBP-3 is antiproliferative after exogenous expression or treatment." (PMID 39619437, 2024). "Corroborating these observations, elevated IGFBP-3 mRNA is observed in TNBC relative to ER+ breast cancer cells." (PMID 39619437, 2024). "Taken together, these data represent a mechanistic understanding of the regulation of IGFBP-3 in breast cancer cells by Ful and Tam." (PMID 39619437, 2024). "MCF-7 and T-47D cells expressed low but detectable IGFBP-3 (intracellular and extracellular), whereas both MDA-MB-231 and MDA-MB-468 cells had significantly higher levels of IGFBP-3 when compared to ERα positive breast cancer cells." (PMID 39619437, 2024).
breast carcinoma (continued). "have also indicated that IGFBP3 enhances the oncogenesis and development of breast cancer; mechanically, it can upregulate the EGFR phosphorylation and activate the p44/42 and p38 MAPK classical signaling pathways." (PMID 38463397, 2024). "The endogenous expression of IGFBP-3 was profiled in four breast cancer cell lines representing ERα positive and triple-negative clinical subtypes." (PMID 39619437, 2024). "Clinically, higher IGFBP-3 is observed in malignant breast tumors compared to their benign counterparts." (PMID 39619437, 2024). "The effect of IGFBP3 in promoting the growth of breast cancer cell is related to accumulation of damaged T cells." (PMID 37088808, 2023). "Elevated IGFBP3 expression correlates with poor prognosis of pancreatic ductal adenocarcinoma, breast cancer, oral squamous cell carcinoma, papillary thyroid carcinoma and colorectal cancer." (PMID 37088808, 2023). "Using a secretome proteomics approach, IGFBP-3 has also been identified as a secreted mediator of breast cancer cell senescence following chemotherapeutic drug treatment." (PMID 37253773, 2023). "IGF-1 gene expression increases in people with breast cancer compared to healthy people, while the circulating levels of Insulin-like growth factor binding protein 3 (IGFBP-3) will decrease." (PMID 36849958, 2023). "The present study revealed that IGFBP-3 decreases cell viability of the MCF-7 human breast cancer cell line via inducing senescence." (PMID 37253773, 2023). "This study demonstrates that IGFBP-3 inhibits cell proliferation through senescence in MCF-7 human breast cancer cells by inhibiting telomerase activity." (PMID 37253773, 2023). "The expression of IGFBP3 in ovarian cancer, lung cancer, breast cancer, prostate cancer, and gastric cancer has also been reported." (PMID 37088808, 2023). "This study demonstrated that IGFBP-3 induces senescence in MCF-7 human breast cancer cells by inhibiting telomerase activity, thereby reducing cell viability." (PMID 37253773, 2023). "IGFBP3 expression was down-regulated in Her2-positive breast cancer cells with trastuzumab resistance and led to the inhibition of the Wnt pathway and the rise of Cullin7 expression mediated by TCF7L2." (PMID 36660244, 2023). "In breast cancer, IGFBP3 regulates apoptosis through increasing the ratio of proapoptotic (Bax) relative to antiapoptotic (Bcl-2) proteins." (PMID 35871161, 2022). "Given that the ADIPOQ rs7649121 SNP was associated with the IGFBP-3 serum concentration it is not possible to disentangle if the modifying effect was due to a breast cancer signaling pathway or to the effect of the SNP on the IGFBP-3 serum concentration." (PMID 35115550, 2022). "In in vitro experiments, IGFBP-3 enhancement can induce the apoptosis of breast cancer cells, and the low expression of IGFBP-3 indicates a poor prognosis." (PMID 35069971, 2022). "Nine distinct clusters were labeled “#0 human breast cancer”, “#1 electrochemoth therapy”, “#2 anti-tumor effect”, “#3 IGFBP3”, “#4 analogues”, “#5 T7 peptide”“, “#6 nuclear factor-kappa”, “#7 superoxide anion” and “#8 cell survival”." (PMID 36300100, 2022). "Loss of the H3K27me3 signal is associated with the upregulation of several breast cancer oncogenes, such as those encoding epidermal growth factor receptor (EGFR) or insulin like growth factor binding protein 3 (IGFBP3) involved in tamoxifen resistance." (PMID 35453496, 2022). "Loss of PTEN leads to the activation of many kinases and subsequent cell cycle progression, and IGFBP3 has an anti-proliferative effect and induces apoptosis of breast cancer cells." (PMID 35311114, 2022). "IGFBP3-mediated activation of the EGFR and IGF1R has been suggested previously in breast cancer epithelial cells, in which treatment of cells with IGFBP3 resulted in ligand-stimulated EGFR and IGF1R activation and subsequent downstream DNA synthesis." (PMID 36497022, 2022).